INS (insulin)
Diseases named in the same sentence as INS in open-access papers (continued):
Sharing a sentence is not in itself a finding about the gene and the disease.
type 2 diabetes (continued). "In type 2 diabetes, because insulin sensitivity is reduced, the islet cells compensate by producing more insulin and long-term compensation is detrimental to the development of type 2 diabetes." (PMID 34803706, 2021). "It is also predicted that the amount of insulin needed to effectively treat type 2 diabetes will rise by more than 20% worldwide in the next 10 years." (PMID 33807829, 2021). "Type 2 diabetes mellitus (T2DM) occurs when β-cells are unable to release enough insulin to compensate for insulin resistance." (PMID 33514698, 2021). "Alemi and colleagues in a prospective cohort study, found no significant change regarding BP in normotensive patients with type 2 diabetes receiving metformin, glibenclamide + metformin, metformin + insulin or insulin therapy." (PMID 34418281, 2021). "The use of insulin has increased globally, mainly due to the rising prevalence of type 2 diabetes, and will continue to do so." (PMID 33483763, 2021). "MAPK3, and AKT1 were involved in Insulin signaling pathway (hsa04910), and Type II diabetes mellitus (hsa04930)." (PMID 34017037, 2021). "The glucose metabolic weakening in diabetes type 2 is a consequence of modification of various signaling pathways adjusting the uptake of glucose constituting insulin and exercise-enkindled signaling pathways." (PMID 34159199, 2021). "The addition of basal insulin is a well-established approach in patients with type 2 diabetes (T2D) who require intensification of antihyperglycemic therapy." (PMID 33550540, 2021). "In summary, 5‐HT2CR agonists are effective at improving obesity and show therapeutic benefit with respect to glycaemic control and insulin sensitivity in obese individuals with prediabetes or type 2 diabetes." (PMID 33909316, 2021). "Type 1 diabetes is the result of autoimmune destruction of beta cell islets and type 2 diabetes is thought to develop because the release of insulin from beta cells cannot meet the need for insulin." (PMID 34952646, 2021). "A variable combination of impaired insulin secretion and/or reduced insulin resistance results in type II diabetes." (PMID 33587221, 2021). "The purpose of this experiment is to demonstrate the properties of the programs that are relevant for the choice of insulin-based therapy regimens for patients with type II diabetes mellitus." (PMID 33587221, 2021). "We previously found that fetuin-A, a hepatokine increasingly secreted by the fatty liver and a determinant of type 2 diabetes, inhibits glucose-stimulated insulin secretion (GSIS) of human islets." (PMID 33765181, 2021). "Zhu's study found that diet and exercise therapy for obese postmenopausal women can significantly improve blood lipid levels, improve insulin resistance, reduce plasma insulin levels and effectively prevent type 2 diabetes." (PMID 35155511, 2021). "A cancer-promoting effect of insulin has been observed even for exogenous insulin in patients with a long history of type 2 diabetes." (PMID 34681797, 2021). "The present study shows a comparable number of diabetic patients treated with insulin therapy compared to other European preference studies in diabetes type II." (PMID 33587221, 2021). "Insulin saves the lives of patients with insulin-dependent type 1 diabetes (T1D) and is the primary treatment for hyperglycemia in advanced stages of type 2 diabetes (T2D)." (PMID 35056977, 2021). "Patients with type 2 diabetes who received carvedilol treatment reported improvements in metabolic parameters such as insulin sensitivity." (PMID 33855225, 2021). "Several studies had shown that the consumption of yacón has improved parameters related to type II diabetes, improved insulin production and decreased blood glucose levels." (PMID 34202092, 2021). "A study conducted in patients with type 2 diabetes found that consuming CEO causes a significant reduction in fasting blood glucose (FBS), glycosylated hemoglobin (HbA1c), and serum levels of insulin, adiponectin, and TNFα." (PMID 34769261, 2021).
type 2 diabetes (continued). "InsR in muscle also is regulated by Berberine, but mostly, hepatocytes have been studied because hepatic insulin resistance is an important driving force in hyperglycemia and type 2 diabetes." (PMID 34094026, 2021). "In a recent genome-wide association study linking type II diabetes sensitivity with gene expression patterns, the authors showed that PRRX1 is positively linked with insulin sensitivity, supporting the finding that PRRX1 is related to glucose metabolism." (PMID 34496784, 2021). "It is reported that a single bout of exercise increases insulin sensitivity for at least 16 hours' post-exercise in healthy as well as in type 2 diabetes subjects." (PMID 33746668, 2021). "Here, we show that lean mice become insulin resistant after being administered exosomes isolated from the feces of obese mice fed a HFD or from patients with type II diabetes." (PMID 33431899, 2021). "In 2017 (W7), when eGFR results were captured, approximately one in five patients with type 2 diabetes treated with OGLDs alone, one in three patients with insulin-treated type 2 diabetes and one in ten patients with type 1 diabetes had CKD stage 3 or above." (PMID 33594476, 2021). "In conclusion, Zeb1 deficiency mainly affects the endocrine compartment, leading to altered glucose and insulin levels that result in systemic effects by exacerbating disease pathology of type 2 diabetes including accelerated liver steatosis." (PMID 34112759, 2021). "PTP1B acts as a negative regulator for the insulin signalling pathway and a drug target for the treatment of type II diabetes." (PMID 33546180, 2021). "Hypoglycemia is the most frequent adverse effect of intensive insulin therapy in type 1 and type 2 diabetes." (PMID 33898141, 2021). "Metformin is mostly used for the treatment of type 2 diabetes since it decreases glucose production by the liver and increases insulin sensitivity." (PMID 34572814, 2021). "Hypoglycaemia is a common and potentially avoidable adverse event of treatment with insulin or medication which stimulates secretion of insulin in people with type 2 diabetes (T2D)." (PMID 34126938, 2021). "Subsequently, the elevated levels of free fatty acids can impair muscle signaling, promote hepatic gluconeogenesis, and impair glucose-stimulated insulin response, which impact the transition from normal glucose tolerance to type 2 diabetes." (PMID 33613319, 2021). "In a mouse model of type 2 diabetes, dieckol, a phlorotannin isolated from Ecklonia cava was found to significantly reduce blood glucose levels, serum insulin, and body weight." (PMID 34836306, 2021). "The current practice in type 2 diabetes management consists of calculating the required external insulin dose according to blood glucose levels." (PMID 33897704, 2021). "After the meal, insulin concentrations increased in both clusters but were always higher in Cluster 2, despite the same proportion of type 2 diabetes and the exclusion of subjects on insulin treatment for insulin analysis." (PMID 34768690, 2021). "The Wnt signaling pathway is represented multiple times, along with in insulin signaling (normal and diabetic condition) and type 2 diabetes." (PMID 33924951, 2021). "FFA concentrations continued to be significantly higher in the group with type 2 diabetes compared with the other 3 groups under the insulin-stimulated conditions of the HEC." (PMID 33616083, 2021). "In vivo studies of the ethanolic extract have also shown a decrease in the blood glucose level and an increase in the plasma insulin activity in type 2 diabetes mellitus." (PMID 33535455, 2021). "SIRT4 and 7 have been proposed to impede insulin signalling and thus, can contribute to the pathogenesis of type 2 diabetes." (PMID 34071497, 2021).
type 2 diabetes (continued). "The DEVOTE (Trial Comparing Cardiovascular Safety of Insulin Degludec vs Insulin Glargine in Patients With Type 2 Diabetes at High Risk of Cardiovascular Events) trial randomized 7637 individuals with type 2 diabetes to insulin degludec or insulin glargine." (PMID 34559229, 2021). "The proportion of the type 2 diabetes patients using insulin monotherapy (20.5%) or oral glucose-lowering agents was equal (20.3%)." (PMID 34134677, 2021). "From this study, the authors found that there are significant improvements in the levels of fasting glucose, fasting insulin, and HbA1c in patients with diabetes (individuals with both type 1 and type 2 diabetes)." (PMID 35118103, 2021). "There were differences in the values of some metabolites between the patients with type 2 diabetes included in the dapagliflozin and insulin groups at baseline; however, these can be attributed to the lack of randomization." (PMID 33592103, 2021). "Third, as this was a single-centre study, multi-centre studies are needed to further explore the relationship between insulin treatment and atherosclerosis in type 2 diabetes." (PMID 33598483, 2021). "People with type 2 diabetes and hospitalization more often received insulin (55%) than comparisons (45%), and 45% discontinued insulin or stopped all glucose‐lowering therapy after first hospitalization." (PMID 34277957, 2021). "ischemic heart disease) and metabolic disorders (obesity, reduced tissue sensitivity to insulin, type 2 diabetes)." (PMID 34606496, 2021). "We evaluated the safety and efficacy of fully closed-loop insulin therapy compared with standard insulin therapy in adults with type 2 diabetes requiring dialysis." (PMID 34349267, 2021). "The main feature that defines type 2 diabetes is insulin resistance, leading to increased insulin production, which can then beget the overload and failure of the pancreatic beta cells." (PMID 34944640, 2021). "Nevertheless, we underscore the importance of extensive evaluation of the models in a larger sample of individuals with type 1 diabetes, insulin-treated type 2 diabetes, or both." (PMID 34166426, 2021). "Many of the liver-secreted proteins that are upregulated in the plasma of subjects with type 2 diabetes were capable of inducing insulin resistance, supportive of the pathophysiological role of hepatokines in metabolic dysregulation." (PMID 34944728, 2021). "There are studies that include PD + EX which conclude that the Paleolithic diet is a powerful tool to improve body composition and metabolic balance, including insulin sensitivity, glycemic control, and leptin in individuals with type 2 diabetes." (PMID 33801152, 2021). "Type 2 diabetes is a condition characterised by peripheral insulin resistance with inadequate compensatory pancreatic beta-cell insulin secretion." (PMID 34945051, 2021). "As expected, RNA-seq analysis revealed that differentially expressed genes are dominantly enriched in metabolic pathways (including type II diabetes mellitus, the insulin signaling pathway, and the JAK-STAT signaling pathway)." (PMID 34845238, 2021). "Type 2 diabetes (T2D) is characterized by insulin resistance and is diagnosed by biochemical parameters such as high concentrations of serum blood sugar, insulin, and glycosylated hemoglobin (HbA1C)." (PMID 34707665, 2021). "This study provides evidence that fully closed-loop insulin delivery can improve glucose control and reduce hypoglycemia compared to standard insulin therapy in adults with type 2 diabetes and ESRD requiring dialysis, in an unrestricted home setting." (PMID 34349267, 2021). "Type-2 diabetes mellitus is a chronic disorder that results mainly from the ineffectiveness of insulin peripheral action or resistance." (PMID 34943221, 2021). "Over 90% of diabetic patients have type 2 diabetes mellitus, which is closely related to insulin, a glucose metabolism hormone secreted by the pancreas." (PMID 34677483, 2021).
type 2 diabetes (continued). "Nocturnal hypoglycaemia was reported from the HAT (Hypoglycaemia Assessment Tool) study, in which 40.6% of patients with type 1 diabetes and 15.9% of insulin-treated patients with type 2 diabetes had ≥1 nocturnal hypoglycaemic episode." (PMID 33672913, 2021). "The failure of these processes, often induced by sustained high-insulin output, results in type 2 diabetes." (PMID 34292976, 2021). "The therapeutic approach aimed at treating obesity is mainly based on the management of insulin sensitivity, thus delaying the onset or progression of type 2 diabetes." (PMID 34451825, 2021). "The literature has already shown that Sweden has a relatively high use of insulin for the treatment of type 2 diabetes compared to other European countries." (PMID 34172020, 2021). "The measured C‐peptide response showed an increase at baseline and during the low dose of infused insulin before MR blockade but only showed an increased at baseline in the individuals with type 2 diabetes compared to healthy controls, following MR blockade." (PMID 34350730, 2021). "The Wnt signaling pathway is represented multiple times, along with insulin signaling and type 2 diabetes." (PMID 33924951, 2021). "In OLETF rats with type 2 diabetes, taurine has been noted to ameliorate hyperglycemia and dyslipidemia, by enhancing insulin sensitivity and by inhibiting leptin secretion." (PMID 36699147, 2021). "The mechanisms involved in type 1 diabetes imply a reduced BMD as a consequence of insufficient anabolic tone from insulin, while in type 2 diabetes, BMD is normal or high, but there is an alteration of bone quality and microarchitecture." (PMID 34445256, 2021). "For this reason, we assessed the urine metabolic profile of patients with type 2 diabetes before and after the administration of dapagliflozin and insulin degludec using 1H-NMR spectroscopy." (PMID 33592103, 2021). "High insulin levels found in prediabetes and early type 2 diabetes can stimulate thyroid tissue hyperplasia, leading to thyroid enlargement and nodule formation." (PMID 34670571, 2021). "This implies that IDegAsp is a better once-daily insulin regimen than other basal insulin regimens for people with type 2 diabetes for insulin dose control as well as glucose control." (PMID 34564455, 2021). "In the present study, the effect of standardized aqueous extract of hydrolyzed edible bird nest (HBN) on metabolic characteristics and insulin signaling pathway in pancreas, liver and skeletal muscle of db/db, a type 2 diabetic mice model was investigated." (PMID 33986669, 2021). "The most common is type 2 diabetes, usually in adults, which occurs when the body becomes resistant to insulin or doesn’t make enough insulin.”." (PMID 34067027, 2021). "In line with the human clock gene mutation studies, rodent models with genetic deletions of core-clock genes (in either a whole-body or a tissue-specific manner) showed INS resistance, obesity, and type 2 diabetes." (PMID 33815298, 2021). "In humans, GLP-1 is more potent than GIP at stimulating insulin release, and its stimulatory effects persist in type 2 diabetes (T2D) patients, while those of GIP diminish." (PMID 34572144, 2021). "Prospective studies indicate that increased insulin secretion and hyperinsulinemia precedes type 2 diabetes in most people." (PMID 33807132, 2021). "Recent evidence suggests that both insulin secretion and resistance are heritable traits and studies have also demonstrated a genetic contribution to defective insulin secretion and resistance in individuals with type 2 diabetes." (PMID 34801028, 2021). "Of clinical importance, thiazolidinediones (TZDs), a major class of drugs for the treatment of type 2 diabetes (T2D), improve whole-body insulin sensitivity through the activation of PPARγ." (PMID 34670478, 2021).
type 2 diabetes (continued). "Recently our lab has identified transforming growth factor‐β stimulated clone 22 D4 (TSC22D4) as a novel regulator of insulin resistance and hyperglycemia in mouse models of type 2 diabetes." (PMID 34319011, 2021). "A regenerative therapeutic approach with insulin‐producing cells derived from stem cells has been investigated for the treatment of severe type II diabetes." (PMID 33759360, 2021). "Metformin is a well-known insulin-sensitizing agent with the primary indication for type II diabetes treatment." (PMID 35011935, 2021). "Type 2 diabetes is characterized by a chronic hyperglycemia, due to resistance to the insulin action in the cells of the body." (PMID 33801208, 2021). "Type 1 diabetes (T1D) and type 2 diabetes (T2D) are both characterized by a progressive reduction of functional mass of insulin-producing β-cells." (PMID 34376240, 2021). "The present study showed that adults with type 1 diabetes had slightly more optimal medication intake and fewer perceived barriers (i.e. lower ASK-12 total score) than adults with non-insulin-treated type 2 diabetes." (PMID 36994341, 2021). "Second, for the first time using low-dose gliclazide, we show that sulphonylureas augment the classical incretin effect in patients with type 2 diabetes, in addition to the known effects on glucose and insulin secretion." (PMID 33693776, 2021). "The failure of glucose-stimulated insulin secretion (GSIS) that characterizes type 2 diabetes has been traced to a reduced expression of beta cell glucokinase activity." (PMID 35052168, 2021). "Recently, there have been published studies that analyze the potential molecular mechanisms that leads from obesity throughout increased inflammation to impair insulin metabolism and even diabetes type 2." (PMID 33917519, 2021). "Based on these findings, the authors suggested a profound reduction in insulin secretion as the critical determinant of progression from normal glucose tolerance to Type 2 Diabetes among individuals of African descent." (PMID 33602978, 2021). "This fatty acid is known for its positive effects on human health by reducing cancer cells and supporting people with diabetes type 2 by increasing insulin secretion." (PMID 33540634, 2021). "Reduced hepatic insulin sensitivity involves postprandial hyperglycemia through hepatic glucose overproduction, and consequently chronic hyperinsulinemia that triggers type 2 diabetes." (PMID 34444712, 2021). "While previous studies showed similar or better health status in people with type 2 diabetes receiving insulin therapy, we found that vitality, general health and barriers to activity were worse in those on insulin therapy." (PMID 33776906, 2021). "It has been shown that β-cell dysfunction is a leading pathophysiological sign of type 2 diabetes, which is characterized by abnormalities in synthesis and secretion of insulin." (PMID 34803706, 2021). "The inhibition of both forms of GSK3 has been demonstrated to be necessary for insulin re-sensitization in muscles and livers of type 2 diabetes." (PMID 34281282, 2021). "TTs and TFs regulate AMPK (AMP-activated protein kinase) signaling; this enzyme monitors the AMP:ADP:ATP ratio in eukaryotic cells, and the AMPK/SIRT1/PGC1α pathway regulates insulin signaling in type 2 diabetic mice." (PMID 33919211, 2021). "The closed-loop insulin delivery system has been shown to improve glycaemic control in individuals with type 1 or type 2 diabetes." (PMID 34166426, 2021). "This is far from an ideal visualization modality in subjects with type 2 diabetes that are severely insulin resistant, which very likely results in less 18FDG uptake by metabolic tissues including BAT." (PMID 34066631, 2021). "Reducing insulin levels in Type 2 diabetes, which is a hyperinsulinaemic condition, should therefore be considered a priority." (PMID 34336909, 2021).